FGFR2 (fibroblast growth factor receptor 2)
Diseases named in the same sentence as FGFR2 in open-access papers (continued):
Sharing a sentence is not in itself a finding about the gene and the disease.
tumor (continued). "We identified a unique and highly complex FGFR2 (fibroblast growth factor receptor 2) tandem duplication with a unique structure specific to each metastatic site—this complex rearrangement was not present in the primary tumor." (PMID 28629429, 2017). "Tumor was not responded to FGFR2 inhibitor and efficacy of immune checkpoint inhibitor needs to be determined." (PMID 28418920, 2017). "Conversely, FGFR2 overexpression increased CD44 and accelerated tumor growth in mice." (PMID 27107424, 2016). "Provided that CD44 is a bona fide GCSC marker and that FGFR2 is the most commonly deregulated RTK pathway in GC, CD44+/FGFR+ GC cells could be a key subset dictating tumor initiation, suggesting some coordination between these two molecules." (PMID 27107424, 2016). "FGFR2 was expressed heterogeneously in the membranes of tumor cells, but not in that of normal epithelial cells." (PMID 26933914, 2016). "bFGF is able to bind FGFR1, FGFR2, and FGFR3, leading to auto-phosphorylation of intracellular tyrosine residues, which are involved in instigating tumor cell proliferation and invasion in various tumor types." (PMID 26824699, 2016). "We examined co-expression of FGFR2 and RSK2 in BCa primary tumour samples." (PMID 27476168, 2016). "In accordance with this hypothesis, cell fractions of unmodified FGFR2+ or CD44+ cell grew faster, formed more tumor spheres in vitro, and established faster growing and larger tumors in vivo." (PMID 27107424, 2016). "However, the mRNA expression of FGFR2 and FGFR3 was comparable between tumor and paired normal tissue." (PMID 26936993, 2016). "In addition, ARQ 087 was effective at inhibiting tumor growth in vivo in FGFR2 altered, SNU-16 and NCI-H716, xenograft tumor models with gene amplifications and fusions." (PMID 27627808, 2016). "Unlike VEGF, FGF2 selectively binds its receptor FGFR2 and stimulates angiogenesis, tumor growth and endothelial cell migration, indicating that FGF2 has biological activity in vivo." (PMID 26575424, 2015). "AZD4547 inhibited tumor regression in FGFR2-amplified xenografts (SNU-16) but not in nonamplified models (AZ521 and MGC803) in that study." (PMID 26000013, 2015). "Through a siRNA library screening that targeted most genes encoding RTKs and subsequent validation, we found that knockdown of 4 RTK receptors (FGFR2, RON, EPHA1, and RYK) via siRNA sensitized MET-addicted tumor cells to PF, while b-FGF-induced activation of FGFR2 conferred resistance to the PF." (PMID 26528757, 2015). "The population of tumor cells with no FGFR2 expression (FGFR2−) displayed significantly slower tumor growth as compared to the FGFR2-expressing tumor cells (FGFR2+)." (PMID 23300950, 2013). "It is also possible that the effect of FGFR2 protein expression is mediated by another cell type, such as fibroblasts, affecting the tumour cell microenvironment, not the tumour cells themselves." (PMID 21418638, 2011). "Based on these transcriptomic results, suppression of CCN2, FGFR2, and SELE may inhibit tumor proliferation, metastasis, or angiogenesis, while upregulation of CDH1 and CXCL10 could enhance cellular adhesion and antitumor immune responses, offering promising avenues for therapeutic intervention." (PMID 40724877, 2025). "Indeed, FGFR inhibitors currently under investigation in other tumor types may offer a promising treatment strategy for GEP-NENs, particularly for G2 tumors with high FGFR2 expression." (PMID 40806365, 2025). "Taking into account the reported oncogenic role of FGFR2 in luminal A BCa, we then evaluated the relationship between FGFR2 and immune markers in relation to the ER status, i.e. in luminal A (n=70) versus non-luminal A tumours (n=29)." (PMID 41018083, 2025).
tumor (continued). "This clinical benefit can be mainly attributed to selective treatment with futibatinib among patients with FGFR2 aberrations leading to the effective abrogation of FGFR-dependent downstream signalling, which promotes cellular proliferation and survival, resulting in potent anti-tumour activity." (PMID 38398088, 2024). "The lack of enrichment of high-level FGFR2-amplified tumours in this study may have contributed to the lack of response to AZD4547." (PMID 38791079, 2024). "However, the phase 3 THOR trial did not include patients with FGFR2 rearrangements, and the presence of FGFR2 gene alterations in tumor tissue is no longer listed as an indication in the final FDA approval of erdafitinib." (PMID 39596194, 2024). "A complete lack of FGFR2 in the entire tumor area was observed in 251 (50.9%) cases." (PMID 38155920, 2023). "No FGFR2 fusion events were observed in NAT or eCCA tumor samples." (PMID 35716043, 2023). "If such patients are considered to be candidates for FGFR2 targeted therapy, an incorrect decision may be made at the screening stage if a negative part of the tumor is accidently selected during immunohistochemical evaluation." (PMID 38155920, 2023). "We also quantitated the percentages of parenchymal cells that were CEBPB+ve or FGFR2+ve in CC and HB tumor and non-tumor livers, and found that the percentages of CEBPB+ve and FGRF2+ve parenchymal cells were not significantly different between the three groups." (PMID 36996081, 2023). "In addition, the mRNA levels of CDK1 showed significant positive correlations with FGF20 in FAP(+) CAFs and FGFR2 in PanCK(+) tumor epithelial cells at EOCC tumor invasive margin, but not at LOCC tumor invasive margin." (PMID 37964075, 2023). "Pre-therapeutic endoscopic tumor biopsies from patients with histopathologic response (Becker-1) showed increased FGFR2 expression by immunohistochemistry, whereas no Becker-2/3 sample (n = 20 with stainable tissue) showed strong staining expression (score 3) of FGFR2." (PMID 35246724, 2023). "Two of the four patients whose primary tumors showed FGFR2 amplification on single-spot TMA but had non-corresponding FGFR2-amplified clones in their metastases showed identical results even on whole tumor blocks, and vice versa for the tumors that had only FGFR2-amplified clones in the metastases." (PMID 36416959, 2023). "Additionally, FGF2/FGFR signaling changes are prevalent in various tumor types, with FGF2 being overexpressed in advanced malignant tumors, FGFR2 inhibitors playing a crucial role in tumor growth and progression, and overcoming anticancer drug resistance through novel extracellular inhibitors." (PMID 38139837, 2023). "No immunostaining (FGFR2-0) of a portion of the tumor was found in 491 (99.6%) GCs." (PMID 35167603, 2022). "Interestingly, a synergistic anti-tumor activity of the two drugs was observed in G03 [FGFR2-amplified and cMet non-amplified but IHC (2+)]." (PMID 35664756, 2022). "Patients with FGFR2 in-frame fusions, frame unknown REs and IGR REs—independently of FGFR2amp status—showed strong tumour responses to pemigatinib therapy, resulting in objective responses or stable disease in 80–100% of patients, irrespective of the diagnosed FGFR2 RE type." (PMID 35948633, 2022). "FGFR2 was identified as a protumor gene, and the FGFR2 CNV gains may result in tumor proliferation." (PMID 35498538, 2022). "The same authors reported that TAS-120, an irreversible pan-FGFR inhibitor, was effective in 4 patients with FGFR2 fusion-positive CCA who developed resistance to previous FGFR inhibition and were selected through examination of serial biopsies, ctDNA, and patient-derived tumor cells." (PMID 36045913, 2022). "According to the GH electronic database, the prevalence of FGFR2/3 fusions in liquid biopsy specimens from patients with aNSCLC was 0.28%, whereas the analysis of TASMC electronic database demonstrated FGFR fusions prevalence in tumor tissue specimens of 0.62%." (PMID 35566609, 2022).
tumor (continued). "A complete lack of FGFR2 in the entire tumor area was observed in 251 (50.9%) GCs." (PMID 35167603, 2022). "Interestingly, in patients carrying FGFR2 fusions and treated with the FGFR inhibitor pemigatinib, it was found a statistically significant inverse correlation between the presence of genomic alterations in any tumor suppressor genes and PFS." (PMID 36046845, 2022). "Using marker-based method, we found here that ESCC tumor burden in vivo could increase the HSC-derived CAF progenitors in BM (defined as FGFR2+CD34+CD45+ cells) and HSC-derived CAF precursors in peripheral circulation (defined as FGFR2+CD34+CD45+Col I+ cells)." (PMID 35941662, 2022). "Furthermore, TAMs also promoted tumor progression under hypoxia by interacting with corresponding receptors, such as EGFR- and FGFR2-promoting tumor cell proliferation, CD44-promoting tumor invasiveness, and VEGF-inducing angiogenesis to increase invasion ability of tumor cells." (PMID 34956900, 2021). "In clinical trials, a 6-fold copy number of FGFR1 and a 4-fold copy number of FGFR2 have been used as inclusion criteria for an expected high FGFR expression status, and these patients typically showed responses to FGFRi treatment as indicated by decreased tumor growth." (PMID 33119860, 2021). "In addition to FGFR2 fusion, 8.7% of CCA tumour tissues have the ROS1 kinase fusion protein." (PMID 33277810, 2021). "Notably, one FGFR1-amplified case (patient 13) and one FGFR2-amplified case (patient 4) showed high-level amplification in the smaller tumour rather than the largest tumour." (PMID 31929516, 2020). "Thus, by targeting FGFR2 and inhibiting EMT, miR-381-3p acts as a tumor suppressor." (PMID 33324542, 2020). "No FGFR2 immunoreactivity was detectable in two tumours (patient 23 and 24)." (PMID 32522271, 2020). "This suggests that FGFR2 might have a broad effect promoting IDC progression towards estrogen-independent basal-like phenotype and application of FGFR inhibitors could increase tumour sensitivity to anti-ER therapies." (PMID 31142340, 2019). "Interestingly, compared with our study, although different techniques and samples types (tumors and circulating leukocytes) were used, some genes described by Ferraresso and colleagues in tumor also presented aberrant methylation in canine leukocyte DNA (KDM4B, HOX, WNT and FGFR2)." (PMID 30908498, 2019). "Both baseline tumor and tumor tissue at acquired resistance exhibited FGFR2 amplification, as determined by fluorescence in situ hybridization (FISH) and immunohistochemistry (IHC) staining for FGFR2, which showed strong positivity in both the membrane and cytoplasm of tumor cells." (PMID 28122360, 2017). "Thus, this is the first report to identify FGFR2 amplification in a CRC tumor sample obtained directly from a patient's primary tumor and the first non-cell-line-derived, clinical case harboring the aberration." (PMID 28835367, 2017). "The lack of widespread staining may in part result from FGFR2 expression heterogeneity, such that a small tumor region with potential positive expression might not be represented by the small array core sample." (PMID 24968263, 2014). "Moreover, FGFR2-expressing human tumor cells were more tumorigenic than FGFR2-negative cells in the xenograft experiments." (PMID 23986719, 2013). "Furthermore, fibroblast growth factor receptor 2 (FGFR2); ARHGEF4, which acts as a guanine nucleotide exchange factor; and SDC1, a member of the syndecan proteoglycan family, were also expressed at significantly lower levels in ulcerated tumours." (PMID 23383013, 2013). "The absence of FGFR-2 in PA is in accordance with thebenign behavior of this tumor." (PMID 20379686, 2010).
tumor (continued). "However, current studies do not distinguish FGFR2 isoforms within circulating tumor cells, which may limit their predictive and clinical utility." (PMID 41584352, 2026). "This molecular screening could avoid the prescription of these drugs to patients (including those with FGFR2 GAs) that are unlikely to respond to these treatments because of inactivated FGFR signalling in tumor tissue, with a significant reduction in terms of clinical and financial toxicities." (PMID 38326380, 2024). "Thus, FGFR2 fusions to a non-dimerizing partner may drive tumor growth targetable with an FGFR inhibitor." (PMID 39759134, 2024). "Furthermore, correlation analysis revealed that an FGFR2 fusion/rearrangement was associated with low levels of Tregs and N2 neutrophils and high levels of N1 neutrophils infiltrating into tumors but not with CD8+ T-cell or macrophage tumor infiltration." (PMID 38986528, 2024). "Therefore, it may be possible that FGFR2 alterations might also contribute to the establishment of a “non-inflamed” tumor phenotype through the downregulation of antigen-presenting machineries." (PMID 37190307, 2023). "Moreover, differently from that found in the cell line, the generic silencing of FGFR2 was able to increase both ZEB1 and Snail1 expression already in untransfected cells, further supporting the hypothesis of the tumor suppressive role of the endogenously expressed FGFR2b." (PMID 26713601, 2016). "But the U2OS cell line negative for FGFR2 displayed a limited sensitivity, and none of them are damaged by unconjugated scFvF7-Fc, implying that scFv is carried out MMAE to FGFR2-positive tumor cells." (PMID 39156005, 2024). "Of six patients whose metastases showed FGFR2-amplified tumor clones on single-spot TMA but not in the primary tumor, we evaluated four patients with whole tumor blocks." (PMID 36416959, 2023). "The differential expression of FGFR1/FGFR2 in invasive GBM cells is reflected in the functional consequences of FGFR1 and FGFR2 knockdown, as only ablation of FGFR1, but not of FGFR2, reduced GBM cell migration and tumor invasion." (PMID 37579831, 2023). "FGFR2 and FGFR3 mRNA expression levels were not significantly different between tumor and tumor-adjacent normal tissues (p = 0.97 and p = 0.9, respectively)." (PMID 36142417, 2022). "Finally, for analyzing the FGFR2 methylation difference between tumor and normal tissues, the methylation profiles were obtained in only 14 cancer types instead of all 32 cancer types from the GSCALite web server, and there were still 18 tumor types lacked the methylation profiles." (PMID 33968743, 2021). "Although bFGF was upregulated both in tumor cells and tumor endothelial cells, expression of FGFR1 and FGFR2 was not affected in this model." (PMID 33804681, 2021). "This interpretation was further supported by use of SNP arrays that identified a breakpoint in the FGFR2 gene with increased copy number toward the 5ʹ end, that was specific to PDX and tumor, and not detected in the matching patient’s blood sample." (PMID 34344433, 2021). "Previous study also indicates that hUCMSCs home to tumor tissues but not to healthy tissues and express multiple chemokine receptors, such as SDFR1, TGFBR3, FGFR2." (PMID 27129156, 2016). "Despite the recent development in the field of second-generation FGFR-specific inhibitors, we and others observed several profound treatment responses in FGFR2-driven CCA with non-selective TKIs, even with reduced treatment doses compared to different tumor entities." (PMID 38346946, 2024). "We found that the tumors with alterations in FGFR2 and IDH1/2 had a “non-inflamed” tumor phenotype." (PMID 37190307, 2023).
tumor (continued). "Even though individual evaluations of FGFR2 and MET might not indicate significant differences between normal and tumor samples, a combined assessment of the expression levels of both genes revealed statistically significant disparities." (PMID 38137393, 2023). "Since we did not know a priori, which “cutoff" value of FGFR2 expression might be biologically relevant, we applied a stepwise explorative approach using OS and TSS as surrogates for a putative tumor biological significance." (PMID 35167603, 2022). "FGFR2 and Met may have specific and overlapping roles, which may not be shared by other RTKs, such as HER2, in tumor malignancies, according to their embryogenic and morphogenic functions." (PMID 35954414, 2022). "The anti-tumour activity of pemigatinib, a selective inhibitor of FGFR 1–3, was evaluated in the phase 2 study FIGHT-202 (NCT02924376) in 146 patients with previously treated metastatic CCA, with and without FGFR2 alterations." (PMID 36046845, 2022). "One limitation of our study was that we did not confirm whether overlapped FGFR2 and HER2 amplification in the tumor was exclusive, because we did not perform multicolor FISH." (PMID 27014419, 2016).